SHH (sonic hedgehog signaling molecule)
Description:
[Sonic hedgehog protein]: Precursor of sonic hedgehog, a morphogen that activates the smoothened signaling pathway, and which is essential for a variety of patterning events during development. The C-terminal part of the precursor displays an autoproteolysis and a cholesterol transferase activity, resulting (1) in the cleavage of the full-length protein into two parts, Sonic hedgehog protein N-product and C-product (ShhN and ShhC, respectively) and (2) covalent attachment of a cholesterol moiety to the C-terminus of the newly generated ShhN (By similarity). Both autoproteolysis and a cholesterol transferase activities occur in the endoplasmic reticulum (By similarity). Following additional lipidation, ShhN acts as a morphogen, while ShhC is degraded in the endoplasmic reticulum (By similarity). [Sonic hedgehog protein N-product]: The dually lipidated sonic hedgehog protein N-product (ShhN) is a morphogen that activates the smoothened signaling pathway, and which is essential for a variety of patterning events during development. Acts by binding to the patched receptor (PTCH1 or PTCH2), relieving smoothened (SMO) inhibition by patched, activating the smoothened signaling pathway and transcription of target genes. In the absence of SHH, patched represses the constitutive signaling activity of SMO. ShhN is widely expressed and plays a key role in the patterning of the central nervous system and limb development (By similarity). Induces ventral cell fate in the neural tube and somites (By similarity). Involved in the patterning of the anterior-posterior axis of the developing limb bud (By similarity). Essential for axon guidance (By similarity).
Synonyms: ShhNC; HHG1; SMMCI; TPT; TPTPS; MCOPCB5; HLP3; HPE3
Tractability: Small molecule: a structure with a bound ligand is known; a high-quality ligand is known; it belongs to a druggable protein family. Antibody: UniProt places it where antibodies can reach, with high confidence; its Gene Ontology location is reachable by antibodies, with high confidence; UniProt predicts a signal peptide or a membrane-spanning region. PROTAC: a small molecule that binds it is known.
Gene: Protein-coding gene on chromosome 7 (155,799,980 to 155,812,463, reverse strand). Ensembl gene ENSG00000164690.
Subcellular location: Endoplasmic reticulum membrane (Sonic hedgehog protein); Golgi apparatus membrane; Secreted (Sonic hedgehog protein N-product); Cell membrane
Pathways (Reactome):
Signal Transduction: Activation of SMO; Class B/2 (Secretin family receptors); Hedgehog 'on' state; Hedgehog ligand biogenesis; Ligand-receptor interactions; Release of Hh-Np from the secreting cell
Developmental Biology: Developmental Lineage of Multipotent Pancreatic Progenitor Cells; Formation of axial mesoderm; Formation of lateral plate mesoderm
Disease: HHAT G278V doesn't palmitoylate Hh-Np; Hh mutants are degraded by ERAD
Gene Ontology:
Molecular function: calcium ion binding; patched binding; protein binding; zinc ion binding; cholesterol-protein transferase activity; endopeptidase activity; laminin-1 binding; morphogen activity; glycosaminoglycan binding
Biological process: CD4-positive or CD8-positive, alpha-beta T cell lineage commitment; epithelial-mesenchymal cell signaling; lymphoid progenitor cell differentiation; metanephric collecting duct development; positive regulation of cell division; positive regulation of cell population proliferation; positive regulation of DNA-templated transcription; positive regulation of sclerotome development; positive regulation of smoothened signaling pathway; regulation of protein localization to nucleus; smooth muscle tissue development; smoothened signaling pathway; androgen metabolic process; apoptotic signaling pathway; axon guidance; branching involved in blood vessel morphogenesis; branching involved in ureteric bud morphogenesis; branching morphogenesis of an epithelial tube; cell development; cell fate specification; cell-cell signaling; central nervous system development; cerebellar granule cell precursor proliferation; determination of left/right asymmetry in lateral mesoderm; dopaminergic neuron differentiation; and 57 more
Cellular component: endoplasmic reticulum; extracellular matrix; extracellular region; Golgi apparatus; cell surface; cytosol; endoplasmic reticulum lumen; membrane raft; plasma membrane; endoplasmic reticulum membrane; Golgi membrane; membrane
Genetic constraint (gnomAD): Loss-of-function variants: 4 observed, 18.58 expected, observed/expected ratio (o/e) 0.22, 90% interval 0.1 to 0.49. The synonymous counts are far from expectation, so gnomAD's model fits this gene poorly and the ratio says little. Missense variants: 499 observed, 530.69 expected, observed/expected ratio (o/e) 0.94, 90% interval 0.87 to 1.01. Synonymous variants: 351 observed, 265.94 expected, observed/expected ratio (o/e) 1.32, 90% interval 1.21 to 1.44.
Homologues: Orthologues: chimpanzee SHH (99% identical), macaque SHH (97% identical), pig SHH (92% identical), rabbit SHH (92% identical), guinea pig SHH (90% identical), rat Shh (88% identical), mouse Shh (87% identical), dog SHH (75% identical), tropical clawed frog shh (66% identical), zebrafish shha (65% identical), zebrafish shhb (62% identical), Caenorhabditis elegans wrt-6 (24% identical), and 18 more. Paralogues in human: IHH (56% identical), DHH (51% identical).
Diseases named in the same sentence as SHH in open-access papers:
SHH is named in the same sentence as 371 diseases in open-access papers, as found by Europe PMC text mining. Sharing a sentence is not in itself a finding about the gene and the disease. The quoted sentences say what the papers report.
medulloblastoma (427 papers, 2008 to 2026). A malignant, invasive embryonal neoplasm arising from the cerebellum. "Survival was highest for patients with the SHH molecular variant (77.8%) and lowest for group-3 medulloblastoma (41.4%)." (PMID 40002185, 2025). "In contrast, medulloblastomas that are associated with alterations in the SHH pathway tend to maintain a more intact BBB, which renders them less responsive to chemotherapy." (PMID 40948505, 2025). "A third of patients with the pediatric cerebellar tumor Medulloblastoma (MB) have mutations that activate Sonic hedgehog (SHH) signaling (SHH-MB subgroup)." (PMID 40766638, 2025). "For example, SHH-subtype medulloblastomas are often driven by mutations affecting the SHH pathway, leading to differential sensitivity to therapies targeting oxidative phosphorylation or lipid metabolism." (PMID 40868156, 2025). "Alterations in the SHH gene are frequently linked to the desmoplastic subtype of medulloblastoma (OMIM 600725)." (PMID 39022728, 2024). "As in other series, the median age of patients was in the late 20 s, the majority of patients had a SHH-activated medulloblastoma and were considered standard-risk." (PMID 36920679, 2023). "This gene has multiple functions, including interaction with proteins in the SHH pathway as well as that of beta-catenin inactivation, both of clinical and diagnostic importance in medulloblastoma." (PMID 37510143, 2023). "WNT signaling activation in the lower rhombic lip progenitor cells causes WNT-activated medulloblastoma, while upregulated SHH signaling in the cerebellar granule neuron precursors of the external granule cell layer leads to SHH medulloblastoma." (PMID 37510143, 2023). "One of these was found to correspond to the Sonic Hedgehog (SHH)-activated medulloblastomas of adult patients with mutation landscapes dominated by the age-associated CpG>TpG substitutions." (PMID 37420249, 2023). "Germline loss-of-function (LOF) variants in ELP1 have recently been strongly associated with medulloblastoma in pediatric age, predisposing a patient to tumor development in combination with constitutive activation of Sonic Hedgehog (SHH) signaling." (PMID 38139220, 2023). "Taladegib is currently being investigated in a phase II clinical trial (NCT05199584) involving patients with solid tumors and PTCH1 loss of function mutations, which is a common mutation in SHH-activated medulloblastomas." (PMID 37568705, 2023). "Hyperactivation of the SHH cascade in basal cell carcinoma and medulloblastoma is mainly due to repressive mutations in PTCH or activating mutations in SMO." (PMID 37149646, 2023). "Medulloblastoma is comprised of four main molecular subgroups that are prognostic with sonic hedgehog (SHH), Group 3 and Group 4 tumors associated with worse prognoses than wingless (WNT) tumors." (PMID 37035203, 2023). "Together, drug-induced mutations in the SHH pathway were observed in four of six versus zero of 10 (66.67% vs. 0%, P = 0.008) SHH medulloblastomas in the SD-CSC versus SI-CSC subtypes, respectively." (PMID 36688010, 2022). "We unravel that aberrant expression of the primate-specific lncRNA HedgeHog Interacting Protein-AntiSense 1 (HHIP-AS1) is a hallmark of SHH-driven tumors including medulloblastoma and atypical teratoid/rhabdoid tumors." (PMID 35831316, 2022). "Medulloblastoma subtypes potentially have different cells of origin based on the key pathways that are altered, e.g., the Wnt/beta-catenin or sonic hedgehog (SHH) mutated tumours." (PMID 35782058, 2022).
medulloblastoma (continued). "These SHH pathway mutations have been previously reported in SMOi-resistant medulloblastomas and BCCs." (PMID 36688010, 2022). "WNT and SHH subtype medulloblastomas result from mutations in the WNT and SHH signaling pathways, respectively, while Groups 3 and 4 medulloblastoma etiologies require further elucidation." (PMID 35565414, 2022). "Together, these findings can explain the preference for SUFU mutations in infant medulloblastoma and suggest that drugs targeting the downstream SHH pathway will be most appropriate for infant patients." (PMID 35535520, 2022). "The ELP1-medulloblastoma syndrome is caused by heterozygous pathogenic germline variants in the ELP1 gene and characterized by an increased risk of sonic hedgehog (SHH)-activated medulloblastoma during childhood." (PMID 35969220, 2022). "Medulloblastoma is causally linked to mutations in the SHH pathway that signals through the primary cilium." (PMID 35295905, 2022). "Gorlin syndrome is a genetic condition associated with the occurrence of SHH activated medulloblastoma, basal cell carcinoma, macrocephaly and other congenital anomalies." (PMID 34888241, 2021). "The dysregulated SHH pathway is associated with bone and soft tissue sarcomas, GLIomas, medulloblastomas, leukemias, and tumors of breast, lung, skin, prostate, brain, gastric, and pancreas." (PMID 33494284, 2021). "BOC is a driver of SHH signaling and is associated with granule cell precursor proliferation and medulloblastoma tumorigenesis; inactivation is associated with decreased medulloblastoma progression." (PMID 34667228, 2021). "Transcriptional regulation by SOX9 has also been associated with the SHH-activated group medulloblastomas." (PMID 34012965, 2021). "These authors showed that, in medulloblastoma tissue, only tumor-associated astrocytes express the SHH protein, suggesting that these astrocytes also secrete this ligand." (PMID 34436033, 2021). "It is known to play a role in tumor microenvironment and is implicated in SHH medulloblastoma tumorigenesis; importantly, its inhibition has shown promise in medulloblastoma therapy." (PMID 34667228, 2021). "Mutations that hyperactivate SHH signaling in CGNPs cause familial medulloblastoma in humans and recapitulate medulloblastoma formation in mice, providing genetically faithful primary tumor models." (PMID 34021242, 2021). "Conversely, overexpression of ATOH1 in a PTCH1-deficient mouse model of SHH-activated medulloblastoma accelerates tumor progression." (PMID 34012965, 2021). "In fact, nearly 90% of sporadic BCC and up to 33% of sporadic medulloblastomas show SHH pathway activation, caused most commonly by inactivating mutations in PTCH1 or more rarely by activating mutations in SMO." (PMID 32957513, 2020). "ARRB1 predominantly functions as an oncogene that positively regulates self-renewal in CSCs with the exception of medulloblastoma CSCs where ARRB1 inhibits SHH/Gli signaling and expression of target genes associated with stemness." (PMID 33297302, 2020). "Germline mutations in SHH receptor PTCH (Gorlin syndrome) and SHH inhibitor SUFU predispose to medulloblastoma, especially infantile forms." (PMID 32903405, 2020). "Further investigation revealed that hotspot U1 mutations were present in about 50% of sonic hedgehog (SHH) medulloblastomas, which represents one group of medulloblastomas." (PMID 32188117, 2020). "Several genes and signaling pathways that direct embryonic developmental processes are also implicated in tumor formation and progression, such as WNT and SHH pathways, and their dysregulation is linked to medulloblastoma formation." (PMID 32316671, 2020). "In other words, the SHH pathway is implicated in several types of cancers, such as basal cell carcinomas, medulloblastomas, gliomas, sarcomas, and pancreatic carcinomas." (PMID 31931858, 2020).
medulloblastoma (continued). "The determination of molecular subgroups—wingless (WNT), sonic hedgehog (SHH), Group 3, and Group 4—of medulloblastomas is very important for prognostication and risk-adaptive treatment strategies." (PMID 32760911, 2020). "Activation of the SHH pathway is also implicated in other cancer types including medulloblastoma and basal cell carcinoma." (PMID 33346248, 2020). "Of the 4 cases described harboring such a mutation 3 fell into the SHH-activated subgroup of medulloblastomas." (PMID 32758285, 2020). "Patients with SHH-driven medulloblastoma frequently exhibit either germline or somatic mutations and copy-number alterations in genes that regulate the Hedgehog (HH) signalling pathway such as PTCH1, SUFU, SMO, GLI1, GLI2 and MYCN8." (PMID 31492956, 2019). "In our screen, CD24+ cells were highly positive for the stem/progenitor marker Sox2, whose expression has been shown to label stem-like cells in the murine brain, and has been shown to be required for SHH-associated medulloblastoma formation." (PMID 30657775, 2019). "Subsequent genetic and molecular analyses revealed that mutations in the Sonic hedgehog (SHH) pathway are common in desmosplastic and extensively nodular medulloblastoma." (PMID 30314361, 2018). "Remarkably, in disagreement with the previous studies supporting a tumor-suppressive role for AMPK in medulloblastoma tumorigenesis, our analysis reveals that loss of AMPKα2 impairs SHH-driven medulloblastoma tumorigenesis." (PMID 30360486, 2018). "Loss of PTCH1 is associated with ~70% of BCCs and 45% of SHH-subtyped medulloblastomas whereas the SMO mutations (such as the constitutively active SMO-M2 [W535L) mutation] is less frequently found in these diseases." (PMID 29348431, 2018). "Here, we describe the analysis of loss of AMPKα2 in a genetically engineered mouse model of SHH-driven medulloblastoma." (PMID 30360486, 2018). "Targeting Smoothened, the positive regulator of the hedgehog pathway, resulted in tumor regression in medulloblastoma patients with SHH mutations." (PMID 28358317, 2017). "Correspondingly, deregulation of signalling pathways important for embryonic brain development (e.g. SHH, Wnt and Notch pathways) appears to be a hallmark of both ependymomas and medulloblastomas and to play essential role in pathogenesis of these tumours." (PMID 28228863, 2017). "Aberrant SHH signaling was first linked to medulloblastoma as Gorlin’s syndrome patients, harboring a mutated PTCH1 gene, exhibited an increased incidence of medulloblastoma." (PMID 29186899, 2017). "Proper identification of SHH activation is also important because a significant fraction of young children with SHH-activated medulloblastomas have underlying germ-line mutations of PTCH1 or SUFU (Gorlin syndrome)." (PMID 27781424, 2016). "The mutation-driven activation of the SHH pathway has been described in basal cell carcinoma and medulloblastoma." (PMID 27825128, 2016). "SMO alterations leading to the activation of the SHH pathway in medulloblastoma are generally related to activating mutations." (PMID 27825128, 2016). "For example, SHH signaling pathway mutations are predominantly associated with nodular/desmoplastic and anaplastic medulloblastomas, which presumably arise from granule neuron precursor cells." (PMID 25571951, 2015). "As much as 50 % (16 of 32) of all Wnt associated medulloblastomas and 11 % (7 of 66) of all SHH associated medulloblastoma cases harbored mutations in DDX3." (PMID 26541825, 2015). "There are currently four recognized subtypes of medulloblastoma, and one involves mutational activation of the sonic hedgehog (SHH) pathway." (PMID 26283963, 2015). "Other components of the SHH pathway, upon mutation, are sufficient to drive medulloblastoma development." (PMID 26512695, 2015). "In contrast, SHH medulloblastoma associated with cluster family B, containing genes enriched for SHH signaling (p = 0.01), as well as extracellular matrix-affiliated pathways (Table." (PMID 25412507, 2014).